CDC42 (cell division cycle 42)
Diseases named in the same sentence as CDC42 in open-access papers (continued):
Sharing a sentence is not in itself a finding about the gene and the disease.
bacterial infection (4 papers, 2013 to 2024). "Overall, these results demonstrate that CDC42-165aa stimulates Pyrin inflammasome by inhibiting CDC42 GTPase activation and provides a potential clinical target for pathogenic bacterial infection in clinical practice." (PMID 38977695, 2024). "Second, during bacterial infection, circCDC42 encodes a unique isoform of CDC42, namely CDC42-165aa, which further regulates Pyrin inflammasome-mediated pyroptosis by inhibiting the GTPase activity of CDC42." (PMID 38977695, 2024). "One explanation is that as a complex condition, bacterial infection eliminates the phosphorylation change of JNK caused by acetylation of CDC42 K153." (PMID 36812247, 2023). "Pathogenic bacterial infection results in CDC42-165aa overexpression encoded by circCDC42 in the lungs, which competitively binds with CDC42 to DOCK8, thereby inhibiting its activation of CDC42, ultimately aggravating Pyrin inflammasome activation and pyroptosis." (PMID 38977695, 2024). "In the present study, acetylation was identified as a novel regulator of CDC42 during bacterial infection." (PMID 36812247, 2023). "Taken together, our findings suggest a new mechanism of bacterial infection-induced promotion of colorectal tumorigenesis by modulation of the CDC42-PAK axis through manipulation of CDC42 acetylation." (PMID 36812247, 2023). "Collectively, the information derived from this study suggests that bacterial infection could promote CRC tumorigenesis by modulating CDC42 acetylation." (PMID 36812247, 2023). "To examine whether Cdc42 is involved in SCV maintenance regulated by SopB and vimentin, we examined the subcellular localization and the active level of Cdc42 upon bacterial infection." (PMID 36717589, 2023).
cardiovascular diseases (4 papers, 2009 to 2024). "Another study reveals that serum CDC42 is decreased in cardiovascular disease patients compared to the controls." (PMID 38476381, 2024).
neurodevelopmental disorder (3 papers, 2021 to 2025). A behavioral and cognitive disorder with onset during the developmental period that involves impaired or aberrant development of intellectual, motor, or social functions. "Recent genetic evidence highlight that the Rac/Cdc42 pathway of which PAK3 is part plays a major role in brain development and functions and its mutational dysfunction leads to neurodevelopmental disorder." (PMID 39806575, 2025).
psychiatric disorder (3 papers, 2020 to 2023). A disorder characterized by behavioral and/or psychological abnormalities, often accompanied by physical symptoms. "The three main Rho GTPases—RhoA, Rac1, and Cdc42, together with their modulators, are known to be involved in many psychiatric disorders that affect the amygdala′s fear conditioning mechanism." (PMID 32858950, 2020). "Notably, a detailed understanding of all these phenomena might be particularly relevant for a better understanding of certain psychiatric disorders, e.g., in schizophrenic patients, in which expression levels of both Cttn and Cdc42 were found to be significantly reduced." (PMID 34360003, 2021).
breast (2 papers, 2013 to 2017). "It has been recently shown that the activity of pro-survival factors downstream of CDC42, such as PAK1 is increased in CDC42-driven colorectal tumorigenesis and these cascade pathways can regulate transcription through transcription factors like NFκB and STAT3." (PMID 28460460, 2017).
inflammation (2 papers, 2022 to 2023). Aberrant reaction of the microcirculation characterized by movement of fluid and leukocytes from the blood into extravascular tissues. "Testing Cdc42 inhibition in an in vivo system of airway inflammation would be a key goal; there are several mouse models of lung inflammation that have been developed." (PMID 36618374, 2022).
nephropathy (2 papers, 2016 to 2019). A nonspecific term referring to disease or damage of the kidneys. "Insufficient Cdc42/Nwasp/stress fibers/YAP pathway activity in podocyte may be one common reason that causes proteinuria in kidney diseases including FSGS and DN." (PMID 26986510, 2016). "Although RhoA, Rac, and Cdc42 are required for normal cellular functions, Rac1 overexpression or activation may be involved in the development of renal diseases, including DN." (PMID 30770784, 2019). "Maintaining necessary Cdc42 would be one potent way to prevent proteinuria kidney diseases." (PMID 26986510, 2016).
neurological diseases (2 papers, 2019 to 2022). "Indeed, chemical modulators for Cdc42, LIMK1, and GSK3β are currently available and several FDA-approved GSK3β inhibitors are already being used in the treatment of neurological diseases." (PMID 31134199, 2019).
blood disorders (1 paper, 2020). "In addition, we suggest thatderegulation of CDC42 may underlie more common blood disorders, such as primarymyelofibrosis." (PMID 32303876, 2020).
cardiac diseases (1 paper, 2015). "The previous studies have also identified additional miR-185 target genes, such as RhoA, Cdc42, and Stim1, that are pro-hypertrophic in the heart, suggesting further that miR-185 is a strong anti-hypertrophic miRNA in vivo and a potent therapeutic target for cardiac diseases." (PMID 25767890, 2015).
genetic disease (1 paper, 2024). "Takenouchi–Kosaki syndrome is a rare genetic disease caused by a mutation in the CDC42 gene." (PMID 39202334, 2024).
skeletal dysplasia (1 paper, 2022). Any Mendelian diseases that affects growth and development of the skeleton. "Consistent with the previous study showing negative mutants of CDC42 inhibit CDC42 signaling and suppressed osteogenesis, our study manifests the attenuated CDC42 signaling in skeletal dysplasia." (PMID 35911831, 2022).
CDC42 also shares sentences with these, for which no sentence is quoted: testicular cancer (5 papers); pancreatic ductal adenocarcinoma (4); Camptodactyly (3); head and neck cancer (3); heart failure (3); multiple myeloma (3); type 2 diabetes (3); acute respiratory distress syndrome (2); alcohol dependence (2); biliary atresia (2); cervical tumor (2); congenital nephrotic syndrome (2); cutaneous melanoma (2); endothelial dysfunction (2); head and neck squamous cell carcinoma (2); holoprosencephaly (2); hypertrophy (2); infectious disease (2); lupus (2); Parkinson (2); Renal cyst (2); sensorineural hearing loss (2); ZIKV infection (2); Aarskog syndrome (1); Adams-Oliver syndrome (1); age (1); allergic disease (1); aplasia cutis congenita (1); atrial fibrillation (1); autoimmune thyroid disease (1).
A further 96 diseases each share a sentence with CDC42 in 1 paper.